TAF11L14 (TATA-box binding protein associated factor 11 like 14)
Gene: Protein-coding gene on chromosome 5 (17,634,460 to 17,635,053, forward strand). Ensembl gene ENSG00000250782.
Gene Ontology:
Molecular function: RNA polymerase II general transcription initiation factor activity; protein heterodimerization activity
Biological process: RNA polymerase II preinitiation complex assembly; transcription initiation at RNA polymerase II promoter
Cellular component: transcription factor TFIID complex; nucleus
Homologues: Orthologues: tropical clawed frog taf11 (43% identical), Drosophila melanogaster Taf11 (42% identical), zebrafish taf11 (41% identical), Caenorhabditis elegans taf-11.1 (33% identical), Caenorhabditis elegans taf-11.2 (27% identical). Paralogues in human: TAF11L2 (87% identical), LINC02218 (85% identical), TAF11L12 (84% identical), TAF11L13 (84% identical), TAF11L10 (82% identical), TAF11L11 (82% identical), TAF11L5 (82% identical), TAF11L6 (82% identical), TAF11L7 (82% identical), TAF11L8 (82% identical), TAF11L3 (81% identical), TAF11L4 (81% identical), and 2 more.